KRT8 (keratin 8)
Diseases named in the same sentence as KRT8 in open-access papers (continued):
Sharing a sentence is not in itself a finding about the gene and the disease.
cervical cancer (7 papers, 2018 to 2025). A primary or metastatic malignant neoplasm involving the cervix. "We detected previously unreported recurrent mutations in cervical cancer in GPX1, MSN, FAS, KRT8, and SPRED3, all genes known to modulate tumorigenic processes." (PMID 34620846, 2021). "Conversely, KRT8/18 depletion results in increased hepatocellular and cervical cancer cell migration and invasion in vitro, while simultaneously sensitizing these cells to cisplatin-induced apoptosis." (PMID 29443941, 2018). "While the importance of KRT8 and KRT15 is rarely reported in cervical cancer, these findings offer opportunities to identify new therapeutic targets and develop targeted treatment strategies." (PMID 39354287, 2025). "KRT8 and KRT15 increase progressively with the development of cervical cancer." (PMID 39354287, 2025). "The increased sample size enabled identification of SMGs previously unreported in cervical carcinoma including NBPF10 (8%), RANBP2 (6%), MSN (6%), KRT8 (6%), POTEC (6%), ZC3H11A (4%), BMS1 (4%), GPX1 (3%), OTOP1 (3%), DNAH12 (2%), COIL (2%), TBC1D26 (2%), SPRED3 (2%), FAM115A (2%), and ARIH1 (1%)." (PMID 34620846, 2021). "In summary, the majority of cervical cancers can be divided into two groups on the basis of molecular signatures: SCCs most probably originate from the KRT5+ squamous lineage of the ectocervix, whereas ADCs most probably originate from the KRT7+KRT8+ columnar lineage of the endocervix." (PMID 33462395, 2021).
liver disease (7 papers, 2013 to 2022). "Among those characterized are keratin-8 mutations associated with liver disease, linking amyloid aggregation to liver pathology." (PMID 35637421, 2022). "This variant is predicted to be deleterious by at least one algorithm, while other mutations in KRT8 have been connected with the development of various liver diseases, including biliary atresia and cirrhosis." (PMID 28626473, 2017). "Patient number 2 possessed a rare variant in the gene connected with other liver diseases: KRT8 (cryptogenic cirrhosis)." (PMID 28626473, 2017). "Mutation in KRT8 is reported to be involved in human liver disease." (PMID 23991084, 2013). "Genetic mouse models highlighted the function of KRTs in protecting hepatocytes from apoptosis and necrosis, and mutations within the KRT8 and KRT18 genes are linked to the progression of liver disease of multiple etiologies." (PMID 31216713, 2019). "The observation that KRT8 and KRT18 variants associate with progression of fibrosis during CHC encouraged us to use hepatitis C virus, a major cause of severe liver diseases, as a pathogenic model." (PMID 31216713, 2019). "For example, the phenotypic characterisation of various K8 and K18 knockout and transgenic mouse lines has been important in helping to demonstrate an association between predisposing KRT8 and KRT18 gene mutations in humans with various types of liver disease." (PMID 23741325, 2013). "Furthermore, aggregated KRT8 is present in Mallory–Denk bodies (MDBs), found in a variety of liver diseases but most predominantly in ASH." (PMID 35637421, 2022). "KRT8 is known to aggregate pathologically, primarily in the form of MDBs in liver disease." (PMID 35637421, 2022). "Although not widely regarded as an amyloid protein, KRT8 is known to aggregate in liver disease within MDBs35, and all three aggregation-promoting mutations analyzed in this study were initially associated with liver disease." (PMID 35637421, 2022).
breast tumors (6 papers, 2007 to 2022). "All analyzed tumors were found to be ERα-negative, negative for or weakly expressing keratin 8, and keratin 14-positive, similar to breast tumors that tend to arise in carriers of BRCA1 pathological variants." (PMID 35393420, 2022). "These included keratin-8 (KRT8), which is often down-regulated in EMT-like breast tumours." (PMID 20628393, 2010).
chordoma (6 papers, 2019 to 2025). Chordomas are rare malignant tumors arising from embryonic remnants of the notochord in axial skeleton. "Genes marked on the volcano plot were either implicated earlier in chordoma biology (e.g. keratins—KRT8, KRT18, KRT19, TBXT, LMX1A, and EGFR) or identified by outstanding p-value (e.g. IL11, CD24), high absolute fold-change (e.g. GABRA1) or DMR result (e.g. MNX1)." (PMID 37434245, 2023). "In another study, KRT8 knockdown suppressed autophagy and overcame chemoresistance of chordoma cells." (PMID 36871041, 2023). "Chordomas contain cells similar to NCs in terms of morphology and express NC-related genes (e.g., T, KRT8/18/19)." (PMID 35359916, 2021). "In the present study, we found the expression of KRT8 was upregulated in two chordoma cell lines, CM319 and UCH1, after the treatment with doxorubicin (Doxo) or irinotecan (Irino)." (PMID 31767864, 2019). "Collectively, in this study, we show that KRT8 executes a cytoprotective action during chemotherapy and endows chordoma cells with greater chemoresistance." (PMID 31767864, 2019). "A most likely explanation is that knockdown of KRT8 successfully blocks the late-stage autophagy and therefore chemosensitizes chordoma cells." (PMID 31767864, 2019). "We then used siRNA to knock down the KRT8 expression of chordoma cells, followed by chemotherapy in vitro." (PMID 31767864, 2019). "Cytokeratin 8 (KRT8) is a molecular marker of notochordal cells, from which chordoma cells were believed to be originated." (PMID 31767864, 2019). "Knockdown KRT8 chemosensitizes chordoma by strikingly aggravating ER stress through the PERK/eIF2α arm of UPR and blocks the late-stage autophagy." (PMID 31767864, 2019). "This study represents the first systematic investigation into the role of KRT8 in chemoresistance of chordoma cells and our results suggest KRT8 as a promising therapeutic target for chemoresistant chordoma." (PMID 31767864, 2019). "As we have clearly showed that knockdown of KRT8 overcomes chemoresistance of chordoma cells by promoting its apoptosis in vitro, to further examine the chemosensitizing effect of siKRT8 in vivo we developed a xenograft model using the CM319 cell line." (PMID 31767864, 2019). "This study represents the first systematic investigation into the role of KRT8 in chemoresistance of chordoma and our results highlight a possible strategy of targeting KRT8 to overcome chordoma chemoresistance." (PMID 31767864, 2019). "Keratin, type II cytoskeletal 8, also known as keratin 8, cytokeratin 8, (KRT8, CK8, K8), a well-known epithelial marker protein, is a molecular marker of notochordal cells, from which chordoma cells were believed to be originated." (PMID 31767864, 2019). "Lastly, a xenograft model using CM319 cell line further confirms that knockdown of KRT8 increases chemosensitivity of chordoma in vivo." (PMID 31767864, 2019). "Consistent with their results, we also find KRT8 plays an important role in chordomas’ apoptosis resistance." (PMID 31767864, 2019). "Then, siRNA-mediated knockdown of KRT8 chemosensitized chordoma cells in vitro." (PMID 31767864, 2019). "As the expression of KRT8 of chordoma cells was upregulated after chemotherapy, we hypothesized that KRT8 plays a potential role in the chemoresistance of chordoma cells." (PMID 31767864, 2019). "As we have showed that chemotherapy could promote autophagy activity in chordoma cells, we further investigated the autophagy flux in cases where KRT8 was knocked down followed by chemotherapy." (PMID 31767864, 2019). "In addition, knockdown of KRT8 sensitizes both CM319 and UCH1 cell lines to both Doxo and Irino, which shows that KRT8 may serve as a universal therapeutic target for chemoresistant chordoma." (PMID 31767864, 2019).
chordoma (continued). "The data from this study are the first to provide compelling evidence that upregulation of KRT8 is one of the mechanism responsible for the chemoresistance of chordoma cells and provided a potential therapeutic approach to overcome chemoresistance of chordoma cells." (PMID 31767864, 2019). "Therefore, we hypothesized that KRT8 plays a potential role in chemoresistance of chordoma cells." (PMID 31767864, 2019). "As we have demonstrated that chemotherapy induced UPR in chordoma cells, we further investigated the activation of UPR in cases where KRT8 was knocked down, followed by chemotherapy." (PMID 31767864, 2019). "Then, our data show that siRNA-mediated knockdown of KRT8 alone do not promote cell apoptosis, nor does it induce UPR and autophagy in chordoma cells." (PMID 31767864, 2019). "However, we do not observe an increased expression of FAS after knockdown of KRT8 alone or followed by treatment of Doxo or Irino as determined by qRT-PCR, and this may due to the low expression of FAS in chordoma cells (data not shown)." (PMID 31767864, 2019).
colitis (6 papers, 2015 to 2024). Inflammation of the colon. "We utilized Cre-Lox-based inducible keratin 8 deletion in mouse intestinal epithelium to characterize the earliest events after keratin 8 loss leading to colitis." (PMID 37962942, 2024). "In addition to its use as a pan-cancer biomarker and expression associated with multiple cancers, KRT8 maintains gut microbiota homeostasis as well as reduces colonic permeability, which is important in protecting against inflammation leading to colitis and colitis-associated tumorigenesis." (PMID 36011407, 2022). "Therefore, the increased levels of PBLD, FAM3D, KRT8, SULT2B1, GPA33, DEPTOR, and decreased expression of ACSL4, IFITM1 and HSD11B1 caused by mEVs has been demonstrated to attenuate colitis, implying that consumption of mEVs has the potential to improve intestinal health." (PMID 35893911, 2022).
colorectal cancer (6 papers, 2009 to 2023). A primary or metastatic malignant neoplasm that affects the colon or rectum. "CK18 is with keratin 8, a proven marker of colorectal cancer." (PMID 36902094, 2023).
pancreatitis (5 papers, 2016 to 2024). Inflammation of the pancreas. "KRT8 (keratin 8) has been identified as having its mutations associated with the occurrence of inflammatory diseases such as chronic liver disease, pancreatitis, and inflammatory bowel disease." (PMID 35578692, 2022). "Gene polymorphism of KRT8 was found in some pancreatitis patients based on a large population-based study." (PMID 35958278, 2022). "Even so, studies on KRT8 in pancreatitis have mostly focused on mutations and sequence variants." (PMID 35958278, 2022). "Next Generation Sequencing was performed to analyze a panel of nine genes associated with pancreatitis (CaSR, CFTR, CPA1, CTRC, CTSB, KRT8, PRSS1, PRSS2, and SPINK1)." (PMID 38927485, 2024). "In murine pancreatitis models, KRT8 was significantly upregulated in pancreas tissue compared with the control group." (PMID 35958278, 2022). "In this study, these datasets were reviewed and we found a great number of genes that were differently expressed between pancreatitis samples and control samples, including murine Krt8 and Nmd3 (148 genes in AP models and 1195 genes in CP models)." (PMID 35958278, 2022). "KRT8 was found to be upregulated in murine pancreatitis tissue, human CP tissue, and human PDAC tissue." (PMID 35958278, 2022). "We found that KRT8 was upregulated in the context of pancreatitis and PDAC in an incremental manner and could serve as a diagnostic and prognostic factor for PDAC patients." (PMID 35958278, 2022). "Zhong and Omary found reactive upregulation of KRT8 in caerulein-induced mouse pancreatitis models." (PMID 35958278, 2022). "However, the role of KRT8 in pancreatitis and PDAC is still poorly understood." (PMID 35958278, 2022). "KRT8 is upregulated in pancreatitis and PDAC in an incremental manner, indicating that KRT8 can play a role in the development from pancreatitis to PDAC." (PMID 35958278, 2022). "KRT8 was proven to have better potential as a biomarker of PDAC and pancreatitis for the following reasons." (PMID 35958278, 2022). "Moreover, they demonstrated that in benign lesions, KRT8 might serve protective roles, indicating that the function of KRT8 might change as the disease developed from pancreatitis to PDAC, accompanied by the change of KRT8 expression." (PMID 35958278, 2022). "Importantly, the ectopic expression of ST6GAL1 in acinar cells induces a pronounced upregulation in a ductal gene network (in the absence of either pancreatitis or the KRAS oncogene), as evidenced by RNA-Seq results and staining of SC tissues for SOX9, KRT8, and KRT19." (PMID 37643018, 2023).
triple-negative breast carcinoma (5 papers, 2014 to 2024). An invasive breast carcinoma which is negative for expression of estrogen receptor (ER), progesterone receptor (PR), and human epidermal growth factor receptor 2 (HER2). "To summarise, we found that both Vimentin and Keratin 8/18 accumulated near the nucleus in the triple-negative breast cancer cells." (PMID 38891038, 2024). "Specially, gene KRT8 is also found in the triple-negative breast cancer dataset, which may be a generic cancer gene." (PMID 34095314, 2021).
cystic fibrosis (4 papers, 2011 to 2022). Autosomal recessive disorder caused by pathogenic variants in the CFTR gene (cystic fibrosis transmembrane conductance regulator), which encodes a chloride and bicarbonate channel expressed in epithelial cells, and follow the diagnosis criteria. "The interaction of KRT8 with the CFTRΔF508 mutant, the most common mutation in patients with cystic fibrosis, at nucleotide-binding domain 1 (NBD1) inhibits the translocation of CFTR to the cell surface." (PMID 36231117, 2022). "KRT14 and KRT8 was previously found to be overexpressed in cystic fibrosis at both RNA and protein level." (PMID 27533088, 2016).
granulosa cell tumor (4 papers, 2016 to 2022). A slow-growing, malignant tumor, characterize by the presence of granulosa-like cells and Call-Exner bodies, that is almost always found in the ovary. "Expression of KRT8 or other keratins was also observed in subsets of abnormal granulosa cells in other mouse models for granulosa cell tumors and in KGN cells, a cell line originating from a human adult granulosa cell tumor." (PMID 36430923, 2022). "KRT8 can mediate resistance to apoptosis in granulosa cell tumors by intervening in cell surface death receptor Fas (FAS) expression." (PMID 30634629, 2019). "Expression of KRT8 has been shown to be increased in mouse granulosa cell tumors." (PMID 27344183, 2016).
inflammatory bowel disease (4 papers, 2014 to 2024). A spectrum of small and large bowel inflammatory diseases of unknown etiology. "Of interest, recent studies have demonstrated that mutations in Keratin 8/18 in colonic epithelial cells are associated with loss of permeability control in inflammatory bowel disease." (PMID 35360746, 2022).
lung disease (4 papers, 2021 to 2024). "In lung disease, persistence of KRT8-expressing aberrant basaloid cells in the alveolar epithelium is associated with impaired tissue regeneration and pathological tissue remodeling." (PMID 39358385, 2024). "KRT8 plays an important role in normal lung development and lung disease." (PMID 35664775, 2022).
non-small cell lung carcinoma (4 papers, 1999 to 2024). A group of at least three distinct histological types of lung cancer, including non-small cell squamous cell carcinoma, adenocarcinoma, and large cell carcinoma. "Based on clinical research, the expression of keratin 8 is significantly higher in patients with non-small cell lung cancer (NSCLC) compared with small cell lung cancer (SCLC) patients, and high expression of keratin 8 enhances tumor progression and indicates poor prognosis." (PMID 39739089, 2024).
ovarian tumors (4 papers, 2009 to 2023). "It is interesting to note the focal expression of KRT8 in late-stage ovarian tumors in both TGFBR1-CACcre and TGFBR1-CAAcre mice." (PMID 27344183, 2016).
adenoma (3 papers, 2006 to 2020). A neoplasm arising from the epithelium. "The expression levels of KRT8 were consistent between adenoma (median Ct value=20.1, IQR 19.7–20.9) and normal samples (median Ct value=20.6, IQR 19.4–21.2)." (PMID 16523202, 2006). "For module yellow, which is progressively up-regulated from normal stroma to adenoma to mCA, the top candidate hub genes consisted of CDH1, ST14, EHF, KRT8, and KIAA1217, all of which have important roles in epithelial cells, and/or are associated with tumour malignancy." (PMID 32218455, 2020).
alcoholic steatohepatitis (3 papers, 2021 to 2025). "For example, the G62C missense mutation in the keratin-8 head domain results in the formation of amyloid aggregates, which are believed to contribute to alcoholic steatohepatitis of the liver." (PMID 40076540, 2025). "Aggregated KRT8 is found in Mallory–Denk bodies, observed in hepatocytes of livers with alcoholic steatohepatitis (ASH)." (PMID 35637421, 2022). "Composed primarily of aggregated KRT8 and lesser amounts of KRT18, MDBs are cytoplasmic inclusions that occur within hepatocytes most frequently in alcoholic steatohepatitis (ASH) or alcoholic cirrhosis." (PMID 35637421, 2022). "Ubiquitinated KRT18, KRT8, and sequestosome 1/p62 are the main components of Mallory–Denk bodies (MDB) specific for alcoholic steatohepatitis and NASH." (PMID 34063343, 2021).
asthma (3 papers, 2016 to 2024). "SERPINE1, ABCA1, and KRT8 showed higher expression in bronchial biopsies than the pure bronchial epithelium, in moderate and severe asthma, with and without oral steroid use." (PMID 34088958, 2021).
clear cell renal cell carcinoma (3 papers, 2017 to 2020). "have suggested that KRT8 up-regulation promotes metastasis of clear cell renal cell carcinoma." (PMID 32519739, 2020).
COVID-19 (3 papers, 2022 to 2024). A disease caused by infection with severe acute respiratory syndrome coronavirus 2. "Besides PARP9, the three genes KRT8, SEC14L1, and ALCAM have also been linked to COVID-19." (PMID 38666857, 2024). "In particular, KRT8 (cg03870777) is a marker of DATP representative immunofluorescence staining for pro-SPC, KRT8, and DAPI in both control and COVID-19 lung tissue." (PMID 38666857, 2024).
diabetes (3 papers, 2025 to 2026). "Additionally, markers of keratinization, including Sprr1a, Krt8, and Ivl, were downregulated in the diabetes group but were upregulated following C-dots treatment." (PMID 40154736, 2026). "Several genes, including GRASP, KRT8, MYZAP, PRKG1, and SMIM24 were differentially expressed in the COVID versus no COVID and diabetes versus no diabetes subgroup analyses." (PMID 40476695, 2025).
fibrosis (3 papers, 2019 to 2024). the formation of excess fibrous connective tissue in an organ or tissue in a reparative or reactive process. "Specifically, we used mRNA expression of Krt8 (indicative of injury/repair), Krt5 (related to dysfunctional repair), Adamts4 (associated with fibrosis), and Itga5 (indicative of damage-responsive fibroblasts)." (PMID 39340037, 2024). "This pattern was further validated with quantitative IF analysis, revealing significantly elevated tubular injury markers Krt8 and Vcam1 in Ecad-positive distal nephron tubular segments compared to proximal tubules in both fibrosis models." (PMID 38172172, 2024).